KRAS (KRas proto-oncogene, GTPase)
Diseases named in the same sentence as KRAS in open-access papers (continued):
Sharing a sentence is not in itself a finding about the gene and the disease.
cancer (continued). "More importantly, G12C, G12D and G12R are involved in the impairment of the KRAS activity and induce malignant tumors." (PMID 35586192, 2022). "Our findings reveal a previously unrecognized mechanism in which NOP56 and mTOR cooperate to play a homeostatic role in the response to oxidative stress and suggest a new rationale for the treatment of KRAS-mutant cancers." (PMID 35039048, 2022). "Aberrant activation of KRAS signaling is common in cancer, which has catalyzed heroic drug development efforts to target KRAS directly or its downstream signaling effectors." (PMID 35966590, 2022). "In 2021, Sotorasib was finally approved by the U.S. Food and Drug Administration for the clinical treatment of KRAS-G12C mutant cancers." (PMID 36430338, 2022). "XPO1, one of the exportins identified, has been found to be a druggable vulnerability in KRAS-mutant cancer cells." (PMID 35839996, 2022). "In this work, we discuss the rational design of KRAS mutant cancer cell targeting dextran-conjugated drug and illustrate its benefits." (PMID 35154474, 2022). "Unfortunately, FTase inhibitors (FTIs) have shown clinically disappointing results in KRAS-mutant cancers, possibly related to the functional redundancy between FTase and GGTase." (PMID 35456940, 2022). "KRAS signaling provides a competitive advantage to cancer cells by participating in central carbon metabolism, increasing glucose uptake and glycolysis to increase the nutrients flux while promoting multiple branching biosynthetic pathways." (PMID 35922812, 2022). "It is evident that a high dose of VC is a powerful approach in inducing the oxidative stress selectively in KRAS-mutant cancer cells due to their enhanced glucose absorption." (PMID 36359850, 2022). "It is also worth noting that there are a number of members of the Ras subfamily of GTPases which are frequently mutated in human cancers, including HRAS, NRAS and most commonly, KRAS, with activating Ras mutations found in ∼20% of cancer patients." (PMID 35119068, 2022). "This establishes that the KRAS G12C inhibitor–resistant cancer cells can potentially respond to selinexor." (PMID 35573474, 2022). "In the single-arm, phase I-II CodeBreaK100 trial, the efficacy and safety of sotorasib were evaluated in different types of KRAS G12C mutant cancers." (PMID 36358848, 2022). "It is now evident that silencing G4 elements in the core promoter region of oncogenes such as KRAS is a highly valuable and new molecular target in the treatment of cancer." (PMID 34489556, 2022). "AMG 510 (sotorasib) was the first drug candidate which demonstrated success in clinical trials for KRAS-mutant cancers, especially NSCLC patients with KRAS-G12C mutation (32.2% achieved objective response and 88.1% achieved disease control)." (PMID 36551637, 2022). "Our study revealed several cancer driver genes that differed between the high and low m5C score groups, including KRAS, FBXW7, and SMAD3." (PMID 35433474, 2022). "BI-3406 reduces GTP-RAS formation, thereby limiting cell proliferation in a variety of KRAS-driven cancers." (PMID 35922812, 2022). "It has been reported that oncogenes such as MYC and KRAS can regulate immune response by suppressing IFN‐I pathways in various cancers." (PMID 35253368, 2022). "MYC is known to cooperate with KRAS in driving many cancers and contributes to many cancer hallmarks." (PMID 35883603, 2022). "It covalently binds to KRAS (G12C) and recruits E3 ligase VHL to rapidly induce KRAS (G12C) degradation and inhibits MAPK signaling in KRAS (G12C) mutated cancer cell lines." (PMID 35922812, 2022).
cancer (continued). "Some of the significant cancer hallmark terms are epithelial-mesenchymal transition (MSX1, CXCL12, SCG2, SLIT2), KRAS signaling up (F13A1, ADAMDEC1), inflammatory response (CCL5, VIP), IL-6/JAK/STAT3 signaling (CXCL13)." (PMID 35486660, 2022). "STAT3 and KRAS mutant proteins have been considered anti-cancer targets; however, they are also considered to be clinically “undruggable” intracellular molecules, except for KRAS(G12C)." (PMID 35886918, 2022). "In this review, we delineate the recent therapeutic strategies for KRAS mutant cancers and discuss the resistance mechanisms of KRAS mutant therapy and the possible approaches to combat them." (PMID 35922812, 2022). "In conclusion, new cancer therapy alternatives against oncogenic KRAS provide safer, less toxic, less off-target, and more patient-specific treatments than classical therapies and several small-molecule drugs." (PMID 35014625, 2022). "Collectively, these results demonstrate that BCL6 expression correlates with poor patient survival in KRAS-mutant cancers, including LUAD." (PMID 36377663, 2022). "With these observations, exploiting macropinocytosis for intracellular drug delivery into KRAS mutant cancer is emerging as a recent exploration." (PMID 35154489, 2022). "Promising results have emerged with KRASG12C inhibitors in NSCLC; in fact, targeting mutant KRAS can reverse the cancer cells’ ability to avoid immune surveillance, and can enhance an immune-attractive microenvironment." (PMID 35646638, 2022). "Increased activation of ERBB1/EGFR as well as of the other ERBB receptors have widespread involvement in cancers including, it has recently been established, in KRAS-induced lung tumorigenesis." (PMID 35971826, 2022). "TCGA databases were utilized to investigate the mRNA expression of KRAS in different tumors and normal tissues of multiple cancer types." (PMID 34255132, 2022). "The human proto-oncogene RAS, which contains three sub-categories (HRAS, KRAS, and NRAS), is one of the most frequently mutated genes in cancers, with gain-of-function mutations occurring in approximately 30% of human malignancies." (PMID 35563733, 2022). "The relationship between YAP and the RAF/MEK/ERK cascade was discovered by genetic screens, which showed that the inhibitory combination of RAF or MEK with YAP has increased efficacy not only in BRAF-mutant cancers but also in KRAS-mutant cancers." (PMID 36483040, 2022). "In this manuscript, we conducted a wide investigation by visualizing the DNA methylation of KRAS in pan-cancer patterns to understand how this important epigenetic mark alters KRAS expression during tumorigenesis." (PMID 35563733, 2022). "Another mechanism that involves the development of so-called adaptive resistance, whereby KRAS-dependent tumors under the treatment pressure converse from one histological type to another, is driven by the primary cancer type." (PMID 36359850, 2022). "A study on the characterization of small snoRNAs in cancer identified an unexpected role for specific snoRNAs in the modulation of KRAS-driven carcinogenesis." (PMID 34489556, 2022). "We performed an integrated analysis of RNAi- and CRISPR-based functional genomic datasets (n = 5) to identify novel genes selectively required for KRAS-mutant cancer." (PMID 35039048, 2022). "Mutant KRAS modulates the metabolic plasticity of cancer cells conferring a growth advantage during hypoxia." (PMID 36550998, 2022).
cancer (continued). "Partial mTORC1 inhibition reserves the limited AAs derived from macropinocytosis, favors the growth of macropinocytosis-dependent cancer cells, and enhances the growth of KRAS-induced pancreatic cancer." (PMID 35177645, 2022). "Recently, Hofmannet.al discovered that the small molecule BI-3406 binding to the catalytic domain of SOS1 can reduce the formation of GTP-loaded RAS, thereby limit the proliferation of cancer cells driven by KRAS." (PMID 36713456, 2022). "Like the cancer-associated mutations, NS-associated mutations result in accumulation of GTP-bound KRAS through enhanced nucleotide exchange or impaired GTP hydrolysis, albeit to a lesser extent than the cancer-associated variants." (PMID 35178568, 2022). "KRAS was known for so long as being one of the ‘undruggables’ and was called the Death Star of cancer targets." (PMID 35234864, 2022). "Even though EGFR-targeted cancer therapy is initially effective against KRAS-wild-type cancers, drug resistance is prevalent in patients receiving several cycles of treatment, highlighting the urgent need to design novel therapeutic modalities." (PMID 35372044, 2022). "The macropinocytosis of extracellular proteins was described previously in PDAC as an endocytic process, exploited by KRAS mutant cancer cells to fuel their central carbon metabolism with amino acids." (PMID 36612058, 2022). "Triple combination therapy, such as anti-PD-L1 antibody, poly-(ADP-ribose) polymerase inhibitor, and MEK inhibitor, was also applied to overcome resistance to anti-PD-L1 therapies in KRAS mutant cancer." (PMID 36003387, 2022). "Standing as the most frequently mutated oncogene in human cancer, with particular relevance in pancreatic, colorectal (CRC) and lung cancers, KRAS is considered a key therapeutic target." (PMID 35805073, 2022). "We determined how KRAS-mutant cancer cells depend on paracrine CCL2 signaling to myeloid cells, including mononuclear and mast cells, to induce vascular permeability and angiogenesis during malignant pleural effusion development." (PMID 35327394, 2022). "We have recently shown that dual inhibition of PLK1 and FGFR1 has synergistic anticancer effects in KRAS-mutant cancer cells, as FGFR1 and PLK1 cooperate control the metabolic stress associated with KRAS mutation." (PMID 36483040, 2022). "Lately, KRAS G12C has been in the spotlight and KRAS G12C-targeted molecules have been developed as potential cancer treatments." (PMID 35806100, 2022). "A well-designed delivery system that enters KRAS mutant cancer cells through macropinocytosis and kills them efficiently while sparing immune cells will be much more promising." (PMID 35154489, 2022). "Alternatively, exploiting a metabolic breach of KRAS-mutant cancer cells related to a glucose-dependent sensitivity to oxidative stress is becoming a promising indirect cancer targeting approach." (PMID 36359850, 2022). "Despite its well-recognized importance in cancer promotion, only a few efforts in the past four decades have resulted in approved clinical therapeutic strategies for KRAS-mutant cancers." (PMID 34489556, 2022). "The KRAS-driven cancers represent highly malignant oncologic disorders with a poor clinical outcome." (PMID 36359850, 2022). "In conclusion, we have shown that the nuclear transport protein XPO1 inhibitor can enhance the anticancer activity of KRAS G12C inhibitors in preclinical cancer models." (PMID 35573474, 2022).
cancer (continued). "IL-1α, which is over-expressed in the TME, induces KRAS mutations in PC patients, while IL-6 regulates STAT3 activation in PC cells and to drive cancer development." (PMID 36578477, 2022). "This role of KRAS as a driver of metabolic changes, such as the Warburg effect for instance, has been frequently reported for several cancers." (PMID 36077838, 2022). "In conclusion, JNK inhibitor co-treatment can enhance the cancer cytotoxic effect of ferroptosis inducers in NRAS and KRAS mutation-harboring cells (HT-1080 and MIA PaCa-2)." (PMID 36232313, 2022). "This work is expected to provide useful information for further understanding function and target roles of KRAS in anti-cancer drug development." (PMID 35425180, 2022). "While Gln deprivation was somewhat toxic to KRas-driven cancer cells by itself, addition of the ACLY inhibitor SB-204990 increased the loss of cell viability." (PMID 36269753, 2022). "Nevertheless, allele-specific inhibitors designed on the basis of structure have become game changers in oncogenic KRAS–driven cancer therapies." (PMID 35014625, 2022). "We studied the novel cancer-related gene KRAS, which belongs to the RAS gene family, in 33 kinds of tumors." (PMID 36330448, 2022). "Inhibition of SOS1 can increase the chemosensitivity of KRAS-amplified cancer cells to MEK inhibition and the SOS1 inhibitor BI-3406 has been demonstrated to synergize with the MEK inhibitor trametinib." (PMID 36048281, 2022). "The GSK3 isoforms had been reported to be essential to the viability of oncogenic KRAS-addicted cancer cells, but to be dispensable to Ras-independent cancer cells." (PMID 35114566, 2022). "This, in turn, suggests that KRAS-mutant CRC is a unique type of cancer, differing in terms of the treatment scheme and prognosis." (PMID 36452508, 2022). "Inhibitors of FTase and GGTase-I are used to target Ras prenylation, especially for KRas proto-oncogene, GTPase (KRAS), which is frequently mutated in many types of cancers." (PMID 35216483, 2022). "Upon KRAS G12C inhibition, subpopulations of cancer cells that enter a quiescent state can stimulate a compensatory increase in active, GTP-bound KRAS G12C protein via EGFR and aurora kinase signaling." (PMID 34990404, 2022). "The existence of targetable oncogenic mutations was excluded by utilizing the Illumina amplicon cancer panel (TSACP), sequencing 212 regions in 48 cancer-related genes including EGFR, BRAF, KRAS, MET, and RET." (PMID 35039644, 2022). "KRASG12C inhibitors not only affect the survival of cancer cells but also can mediate immunomodulatory effects by reversing KRAS-driven immunosuppressive mechanisms and generate a TME that is more favorable for an antitumor immune response." (PMID 35857848, 2022). "We then examine the clinical relevance of KRAS, especially the KRASG12C mutation in human cancer, by providing an in-depth analysis of its cancer epidemiology." (PMID 35045886, 2022).
cancer (continued). "The RAS gene (KRAS, NRAS and HRAS) represents the most frequently mutated oncogenes in human cancers, in particular in pancreatic, lung and colorectal cancers." (PMID 35328482, 2022). "Accordingly, Chapuy and colleagues identified BRAF (6% incidence), KRAS (3%) and MAP2K1 (3%) among candidate cancer genes, and mutations in these genes were mostly clonal." (PMID 35158933, 2022). "Wnt beta-catenin and KRAS signaling was enhanced in EVs, suggesting EVs’ involvement in promoting cancer progression and metastasis." (PMID 35663013, 2022). "Next, we used SurvivalMeth to investigate the correlation between the DNA methylation of KRAS and prognostic values in different cancer types." (PMID 35563733, 2022). "It is important to highlight that the RPE1 cells used in this study, although telomerase immortalized and non‐transformed, do still have mutations in at least two known cancer‐associated genes: CDKN2A and KRAS." (PMID 35037284, 2022). "As previously underlined, KRAS co-occurring mutations are fundamental factors determining distinct immune phenotypes within KRAS-mutant cancers." (PMID 36012655, 2022). "As a KRAS activator, SOS1 can potentiate the effects of KRAS in various cancers; therefore, its inhibitor along with a KRAS inhibitor should cause greater inhibition of the cascade effects than KRAS alone." (PMID 35740545, 2022). "Our data revealed that fibroblast properties were modulated by the cancer cell-secreted factors, mostly independently of KRAS and in a cell line-dependent context." (PMID 36010567, 2022). "Over the past 40 years, great efforts have been made to explore routes for indirect targeting of KRAS mutant cancers, including KRAS expression, processing, upstream regulators, or downstream effectors." (PMID 35922812, 2022). "KRAS promotes the secretion of sonic hedgehog protein (SHH) by cancer cells, which can induce extensive proteomic changes in PSCs." (PMID 36230914, 2022). "The interaction of KRAS and STK11 has also been demonstrated to have prognostic importance across cancers as coalteration of these genes is associated with overall worse prognosis." (PMID 35703181, 2022). "NRAS, along with KRAS and HRAS, constitutes the RAS family, which is the most frequently mutated gene family in cancer." (PMID 36003381, 2022). "In the molecular landscape of LUADs, a mutation in the Kirsten rat sarcoma viral oncogene homolog (KRAS) gene is present in 30% of cases, making it the most frequent oncogenic driver mutation in this cancer type." (PMID 35205778, 2022). "Evidence exists that KRAS- mutant cancers with the G12C subtype, instead of the G12D subtype, was associated with higher TMB and PD-L1 positivity rate compared with wild-type KRAS." (PMID 36741696, 2022). "As endogenous inhibitors, SNORD50A and SNORD50B tightly bind KRAS to weaken KRAS binding to the FTase and SNARE proteins, inhibiting the cancer-causing activities." (PMID 36078062, 2022). "Expression levels of cell-cycle markers such as CDK4 and cyclin B1 were also found to be reduced in both the cancer cell lines as a result of treatment with KRAS G12C inhibitors or their combinations with selinexor." (PMID 35573474, 2022). "To directly test this possibility, we assessed the impact of extracellular lipid restriction in KRAS mutant cancer cells." (PMID 34998392, 2022). "Evidence show that increased expression of miR-124 in cancer cells blocks proliferation by inhibiting the KRas pathway." (PMID 35577881, 2022). "Since the discovery of KRAS in the 1960’s, little progress has been made recently in treating patients with KRAS-driven cancers." (PMID 35045886, 2022). "In line with the KRAS expression in cancers, these results suggest that DNA methylation particulates in the KRAS function in cancers." (PMID 35563733, 2022).